MMP9 (matrix metallopeptidase 9)
Diseases named in the same sentence as MMP9 in open-access papers (continued):
Sharing a sentence is not in itself a finding about the gene and the disease.
emphysema (continued). "Importantly, the mRNA levels of IL-1β, TNF-α, IL-8, IRF-5, IL-18, IFN-γ, TGF-β, matrix metalloproteinase-9 (MMP-9), and MMP-12 were decreased in the FMT-treated emphysema group compared with the emphysema group." (PMID 32681029, 2020). "Increased MMP9, CD147 and cathepsin B levels in ATII cells in emphysema may suggest their contribution to alveolar wall destruction." (PMID 29476075, 2018). "Gal-9 significantly reduced MMP-9, MMP-2 and TIMP-1 levels in BALF on day 7 in the emphysema model." (PMID 28704475, 2017). "MMP-9 is also thought to play an important role in lung remodelling and has been investigated as a potential biomarker of COPD, given that increased elastolytic activity is a significant part of emphysema." (PMID 25849664, 2015). "Indeed, increased lung concentrations of NE, MMP-1, MMP-9, and MMP-12 have been found in CS-exposed mice and emphysema patients, and thus excessive proteolytic activity must be tightly regulated." (PMID 25962837, 2015). "The present results are in accordance with those conclusions, which the upregulation of MMP9 and MMP2 could lead to pulmonary emphysema in rats exposed to WS." (PMID 24802298, 2014). "In addition to MMP9, several animal and genetic studies have connected MMP1 and MMP12 to COPD and emphysema." (PMID 23734748, 2013). "Here, MMP-12 (also termed macrophage metalloelastase MME) has been identified to be of foremost importance in lung destruction, since MMP-12 knockout mice are resistant to smoke induced emphysema, while emphysema can occur independent of MMP-9." (PMID 23720629, 2013). "Both MMP-9 and MMP-12 are likely to be involved in ozone-induced emphysema." (PMID 24260479, 2013). "Interventions directed at inhibiting MMP-9 activity, either alone or in combination with MMP-12 blockers, should be investigated for their potential to attenuate the development or progression of emphysema." (PMID 27234393, 2013). "In smokers with emphysema, MMP-8 and MMP-9 levels in bronchoalveolar lavage (BAL) fluid were significantly higher than in smokers without emphysema." (PMID 23690670, 2013). "MMP-9 is increased in the sputum of COPD patients and MMP-9 activity is known to enhance the degradation of the lung parenchyma thus contributing to the emphysema phenotype observed in COPD." (PMID 23896653, 2013). "For example, mice deficient in MMP-9 develop the same degree of cigarette smoke-induced inflammation and airspace enlargement as control mice and human macrophages MMP-9 mRNA is present in areas of lung irrespective of the presence of emphysema." (PMID 27234393, 2013). "It has been shown that transgenic mice over-expressing MMP1 or MMP9 develop pulmonary changes comparable to human emphysema, and that mice lacking the MMP12 gene are protected from emphysema despite a long term exposure to cigarette smoke." (PMID 23734748, 2013). "Nonetheless, we cannot exclude the possibility that our observations could be attributable to a confounding correlation between MMP-9 and other factors that contribute to COPD exacerbations or the progression of emphysema." (PMID 21429222, 2011). "In addition to elastase, matrix metalloproteinases (MMPs) are known as major contributors to COPD; in particular, levels of MMP9 are increased in the BALF of patients with COPD, and its activity is also elevated in the lung parenchyma of patients with emphysema." (PMID 38891820, 2024). "Ctsl (but not Ctss, Elane, or Mmp9) was highly expressed in eosinophils from emphysema models." (PMID 37816708, 2023). "Furthermore, TIMP-1 preferentially inhibits MMP-9, a key metalloproteinase in the pathogenesis of emphysema; therefore, TIMP-1 may exert protection, while the levels of MMP-9 and the MMP-9/TIMP-1 ratio are reliable predictors of emphysema." (PMID 36835197, 2023).
emphysema (continued). "Attenuating inflammation in the short-term emphysema-exacerbation COPD mouse model; Reducing lung edema and permeability; Decreasing leukocyte infiltration, inflammatory cytokine expression, mucin production, and protease (MMP9 and MMP12) expression in the lung." (PMID 33553219, 2020). "Emphysematous lung tissue destruction is frequently attributed to activation of proteolysis and in particular to Matrix metalloproteinase (MMP) activation, yet our data do not support a role for MMP-2 and MMP-9 in the emphysema development in the copper depleted rat." (PMID 22276220, 2012). "The contribution of MMP-9 to pulmonary emphysema development was indicated by a study of transgenic mice showing that overexpression of this proteinase in macrophages could alter the ECM, leading to the progressive enlargement of air space in lung, which is a similar finding to human emphysema." (PMID 27455234, 2016). "Encouragingly, we verified various well-known mechanistic changes associated with emphysema development, such as NF-κB signaling and TLR4 signaling, as well as increased levels of TNF-α, CSF2, and non-predicted but related interleukins, MPO, and MMP-9 by means of proteomic analysis." (PMID 25962837, 2015). "Furthermore, MMP-9 is markedly activated at AE-COPD, as compared to the stable state, and this activation is independent of clinical characteristics including age, gender, cigarette consumption, severity of obstruction and emphysema as well as infectious agents at exacerbation." (PMID 26126526, 2015). "Disease severity when assessed by the extent of emphysema measured by CT, but not by spirometry or DLco values, was directly associated with sputum MMP-9 concentrations [r = 0.442 (0.171, 0.634), p = 0.020], and MMP-9 activity [r = 0.447 (0.219, 0.643), p = 0.010]." (PMID 27234393, 2013). "Among smokers without COPD, the activities of MMP-9 and TIMP-1 result in recovery and resolution, whereas for smokers with COPD, this results in ECM destruction and emphysema." (PMID 30781876, 2019). "We also checked MMP9, CD147 and cathepsin B mRNA levels by RT-PCR in lung tissue obtained from control non-smokers, smokers and patients with emphysema." (PMID 29476075, 2018). "However, we failed to substantiate our initial assumption that MMP-9, due to its role in ECM turnover, would correlate with DLCO as a functional measure of emphysema." (PMID 36935521, 2023). "Considering the role of MMP9, CD147 and cathepsin B in COPD development, we wanted to check their intracellular levels in ATII cells and lung tissue obtained from patients with emphysema compared to control non-smokers and smokers." (PMID 29476075, 2018).
COVID-19 (133 papers, 2020 to 2026). A disease caused by infection with severe acute respiratory syndrome coronavirus 2. "This was linked to the fact that COVID-19-related pneumonia is characterized by increased fibrosis, reshaping of the extracellular matrix, and increased expression of MMP-9 secondary to inflammation in the lungs." (PMID 37545954, 2023). "The positive correlation between elevated serum MMP9 levels and disease severity reinforces its pathogenic role and resonates with reports linking MMP9 to adverse outcomes in acute respiratory distress syndrome and COVID-19." (PMID 41306770, 2025). "MMP-9 polymorphisms were also reported to increase the susceptibility to COVID-19, especially when accompanied by neurologic symptoms." (PMID 39403255, 2024). "MMP-9 levels were elevated in the serum of COVID-19 patients and were associated with disease severity." (PMID 39403255, 2024). "MMP7 and MMP9 are two enzymes that have been implicated in the context of COVID-19 by interacting with important molecules such as FasL, the respiratory illness caused by the SARS-CoV-2 virus." (PMID 38803919, 2024). "Recent studied revealed that host NEU1 interplay with MMP-9 caused neutrophil overactivation by shedding Sia during severe infections including in sepsis and COVID-19." (PMID 38500102, 2024). "Elevated serum MMP-9 levels have been reported in COVID-19 and were associated with symptom severity." (PMID 39403255, 2024). "In obese diabetics, high serum levels of MMP-9 were related to the severity of COVID-19 when associated with the pro-fibrotic markers PDGF and TGF-β." (PMID 37372128, 2023). "In particular, a strong increase in matrix-metalloproteinase 9 (MMP-9), whose correlation with acute lung injury and chronic respiratory diseases is a fact, has been reported in COVID-19 patients and associated with respiratory failure." (PMID 36674321, 2023). "Increased concentrations of MMP-9 have been linked to a variety of respiratory diseases, such as COVID-19." (PMID 37958192, 2023). "We showed the associations of serum sIL-2R with plasma MMP-9 and lymphocyte counts in COVID-19 with pneumonia." (PMID 36835000, 2023). "MMPs have an essential proinflammatory role in lung diseases, and elevated levels of MMP9 have been reported in patients with severe COVID-19, showing positive correlation with the risk of death." (PMID 37649486, 2023). "MMP-9 levels in the serum of those with COVID-19 have been observed to be elevated, with this associated with the seriousness of the sickness and the probability of death." (PMID 37958192, 2023). "The gene expression of MMP-9 is upregulated in COVID-19 patients, and plasma levels of MMP-9 are directly proportional to the risk of respiratory failure." (PMID 37509076, 2023). "On the other hand, MMP-9 is thought to possibly be implicated in the pathogenesis of neurological symptoms secondary to COVID-19, just as they have also been identified as critical proteins for myeloid cell function." (PMID 37372128, 2023). "Both N-cleaved-Gal9 and sIL-2R levels were associated with plasma matrix metalloprotease (MMP)-9 levels in COVID-19 with pneumonia." (PMID 36835000, 2023). "The expression of MMP9 is increased in COVID-19 patients, and MMP9 plus other genes is associated with patients’ mortality." (PMID 36547446, 2022). "In clinical studies, plasma levels of MMP-2, MMP-3, and MMP-9 were associated with the severity of patients with COVID-19." (PMID 36142454, 2022). "A strength of this study is represented by new findings of an association of MMP3 versus COVID-19 severity and MMP9 versus inflammation." (PMID 35075175, 2022). "Lerum and co-authors recently reported that persistent pulmonary pathology after COVID-19 is associated with high levels of MMP-9." (PMID 36079011, 2022). "As such, the plasmatic levels of MMP2 and MMP9 in patients with severe COVID-19 documented a significant association between their levels and disease severity with the potential to predict the risk of in-hospital death." (PMID 35893698, 2022).
COVID-19 (continued). "Circulating leukocyte count, IL-6, and myeloperoxidase levels were positively correlated with MMP-9 concentration in patients with COVID-19, which suggests that MMP-9 is associated with inflammation in patients with COVID-19." (PMID 36142454, 2022). "It has been also linked to pleural effusions, alveolar damage, and neuroinflammation, which are often seen in COVID-19 patients, and MMP-9 inhibitors were implicated for the therapy." (PMID 34440210, 2021). "Some studies have indicated that the plasma levels of MMP-9 are increased in active COVID-19 patients, as well as suggesting that this increase could be associated with COVID-19 mortality, and it could be an early indicator of respiratory failure." (PMID 40508959, 2025). "Furthermore, COVID-19-associated lung damage has also been shown to be associated with MMPs, for instance, upregulation of gene expression of MMP2 and MMP9 in COVID-19 patients is associated with increased risk of respiratory failure." (PMID 39965032, 2025). "There have been reported that MMP9 is not only associated with the severity and mortality of COVID-19 but also with venous thromboembolism, chronic myocardial fibrosis, and susceptibility to COVID-19-related neurologic syndrome." (PMID 40433617, 2025). "Upregulation of MMP9 by CS and EC+N suggests an increased risk of developing severe COVID-19." (PMID 38991709, 2024). "Diagnostic and treatment methods targeting MMP-9 activity or neutrophil activation may be important in predicting lung involvement in COVID-19 and directing clinical outcomes." (PMID 37545954, 2023). "This study aimed to investigate MMP-9 and TIMP-1 levels in patients diagnosed with COVID-19 and whether the MMP-9/TIMP-1 ratio is associated with lung involvement in COVID-19." (PMID 37545954, 2023). "Increased serum levels of MMP-9 have also been associated with the severity of COVID-19." (PMID 37372128, 2023). "Notably, our observations unveiled the presence of a range of genes linked to inflammation and COVID-19, such as IL-6, basigin, and MMP9." (PMID 37764186, 2023). "Notably, within this pathway, we observed the presence of several genes associated with inflammation and COVID-19 that have been previously identified by other researchers, including IL-6, basigin, and MMP9." (PMID 37764186, 2023). "To investigate whether MMP-9 is involved in sIL-2R release in COVID-19 with lung inflammation, we investigated the associations of sIL-2R levels with plasma MMP-9 and pathological marker levels in CP." (PMID 36835000, 2023). "In patients with COVID-19, increased MMP9 serum levels were associated with increased mortality." (PMID 37834869, 2023). "Additionally, MMP-9 plasmatic levels have been shown to be increased in severe COVID-19 and to be associated with mortality in those patients." (PMID 37509076, 2023). "Additionally, a bioinformatics analysis identified the interaction of these lncRNAs with various miRNAs and genes, including inflammation- and COVID-19-associated genes like IL-6, basigin, and MMP9." (PMID 37764186, 2023). "Furthermore, higher MMP-2 and MMP-9 levels were independent risk factors for mortality in COVID-19 patients." (PMID 36079011, 2022). "Recent data have linked MMP-9 levels to vitamin D in respiratory infections and COVID-19." (PMID 33800947, 2021). "Regarding MMP-9, the plasma levels of this metalloprotease were similar between post-COVID-19 patients and healthy controls (p > 0.05) but were higher in the normal spirometry group than in the abnormal one (p < 0.05)." (PMID 40508959, 2025). "In the presence of delirium, we found elevation of age-corrected blood-levels of GFAP and MMP-9, specifically in COVID-19 patients." (PMID 39352661, 2025). "Here, the ROC curve illuminated the ability of NETRGs to effectively diagnose COVID-19 patients, with MMP9 once again leading the pack, displaying a noteworthy AUC of 0.737." (PMID 40433617, 2025).
COVID-19 (continued). "We observed significantly lower levels of MMP-9 at day 1 in pediatric COVID-19 patients compared to controls (28.14 (16.4,38.6) vs. 100.3 (67.2,882.6) μg/ml, p = 0.005) and UCHL-1 [2.2 (0.7,16.3) vs. 35.2 (10.7,54.3) ng/ml, p = 0.013)." (PMID 39352661, 2025). "In D. Avila-Mesquita’s work, MMP-9 levels were found to be increased by 195.4% in COVID-19 patients compared to controls, and both MMP-2 and MMP-9 levels were associated with mortality risk." (PMID 40943488, 2025). "DPPIV, MMP-8, MMP-9, and MMP-13 levels decreased across COVID-19 variants, suggesting a reduced proteolytic and inflammatory response, consistent with Omicron’s lower severity compared to Alpha." (PMID 40557167, 2025). "Particularly, MMP9 showed the highest diagnostic performance in both diseases, with AUC values of 0.918 and 0.992 for GBS and COVID-19, respectively." (PMID 40433617, 2025). "It was highlighted that MMP-9 levels were significantly higher in COVID-19 patients with neurological symptoms, suggesting a link between MMP activity and neurological complications." (PMID 40943488, 2025). "Studies have shown that matrix metalloproteinase-9 (MMP-9) levels increase significantly in severe COVID-19, with some reports documenting up to 10-fold elevation." (PMID 41503306, 2025). "MMP7-FasL (Healthy), MMP7-FasL (COVID-19), MMP9-FasL (Healthy), and MMP9-FasL (COVID-19) systems showed 0, 1, 4, and 2 salt bridges, indicating MMP9 had more salt bridges." (PMID 38803919, 2024). "MMP9 is a matrix metallopeptidase elevated in the plasma of patients with severe COVID-19 and correlated with in-hospital deaths." (PMID 38991709, 2024). "MMP7 (Healthy, COVID-19) and MMP9 (Healthy, COVID-19) converged to the target of minimization in 644 steps Potential (Energy = −7.6310362e+05), 1014 steps (Energy = −7.7362425e+05); 1910 steps." (PMID 38803919, 2024). "Both MMP7 and MMP9 are being studied as potential biomarkers of disease severity and predictors of clinical outcomes in COVID-19." (PMID 38803919, 2024). "Further research is needed to elucidate the potential interplay between MMP7/MMP9 and FasL and their contributions to COVID-19 pathogenesis." (PMID 38803919, 2024). "A subsequent study confirmed the predictive value of a decreased MMP-9/BDNF ratio for severe COVID-19 outcomes." (PMID 39596862, 2024). "The objective of this study is to evaluate interactions of MMP7/MMP9 with FasL and suggest therapeutic targets against COVID-19." (PMID 38803919, 2024). "It has been observed that in lung tissue from COVID-19 patients, the MMP9 gene is up-regulated, and the protein contributes to cytokine recruitment." (PMID 38243064, 2024). "Four conditions were studied; MMP7/FasL (healthy), MMP7/FasL (COVID-19), MMP9-FasL (healthy), and MMP9/FasL (COVID-19)." (PMID 38803919, 2024). "A recent brain autopsy investigation on individuals who succumbed to COVID-19 yielded significant findings regarding matrix metalloproteinase-9 (MMP-9), which degrades collagen IV, an essential part of the basement membrane." (PMID 40046430, 2024). "Plasma MMP-9 trended higher during COVID-19 in this study but reached statistical significance in other reports." (PMID 38956476, 2024). "Another study described the immune-based signature of COVID-19 patients, relating serum MMP-9 levels with the severity and as a biomarker of COVID-1945,46." (PMID 38243064, 2024). "The best solution of the docked MMP7-FasL and MMP9-FasL was selected to build blood-like conditions resembling healthy patients and special fever and hyponatremia COVID-19-like conditions." (PMID 38803919, 2024). "We analyzed bonds, short-range energies, and free binding energies to draw conclusions on the interaction of MMP7/MMP9 and FasL to gain insights into COVID-19 immunopathology." (PMID 38803919, 2024). "Abnormally high expression of NEU1 interacted with MMP-9, contributed to neutrophil overactivation from COVID-19 patients with severe infections." (PMID 38500102, 2024).